IL10 (interleukin 10)
Diseases named in the same sentence as IL10 in open-access papers (continued):
Sharing a sentence is not in itself a finding about the gene and the disease.
infection (continued). "Furthermore, FMDV WT infection induces production of the anti-inflammatory cytokine IL-10, thus impairing T-cell proliferation with a consequent induction of an anti-inflammatory state." (PMID 36387381, 2022). "Many studies found that decreased IL-10 level in severe infection help patients survive." (PMID 36552302, 2022). "IL-10 plays a central role in infection by limiting the immune response to pathogens." (PMID 35690714, 2022). "Other studies have found that in germ-free zebrafish, Lactobacillus casei BL23 in could effectively promote the expression of pro-inflammatory factors such as TNF-α, IL-10 and IL-1β to fight the infection with Aeromonas veronii." (PMID 35700135, 2022). "The fact that we observed stable IL-10 levels in WT mice already in the steady state suggests that conditioning by endogenous IL-10 might affect the priming of effector cells during infection." (PMID 36618344, 2022). "At this point, we could speculate that these results may be also due to a potential increase in IL-6 and IL-10 levels in the serum of previously infected SARS-CoV-2 females compared to the infection-naive group, as it was observed in a previous study." (PMID 36560410, 2022). "Similarly, interleukin-10 (IL-10) is an important anti-inflammatory cytokine reported to have key role in infection by limiting the immune response to pathogen and thereby preventing the host." (PMID 35277125, 2022). "Moreover, cagA copy number of PMSS1 recovered from wild-type and Il10−/− mice was positively correlated with the capacity to induce IL-8 secretion at four weeks of infection." (PMID 35289715, 2022). "Thus, the confocal microscopy indicates that SDR prior to infection of old mice results in the presence of CD4 T cells in the lung at 60 days expressing markers of IL-10 secreting regulatory cells." (PMID 36189368, 2022). "However, PMΦ from both strains of mice displayed decreased levels of NO, TNF-α, and IL-10 after 30 days of infection compared to the initial days of infection (7 days post-infection)." (PMID 36520787, 2022). "There was evidence of different temporal dynamics in ICUCovid compared to NeuroCovid patients with PPIA, the potent activator of the cytokine storm and MMP-9 inducer, and IL-10, the master regulator of immunity to infection, with the highest levels in ICUCovid patients in the acute phase." (PMID 36591311, 2022). "Additionally, the TNF-α/IL-10 ratio has been previously used as a biomarker for burn injury severity and infection." (PMID 35887586, 2022). "Despite this, BCG vaccination does not appear to overcome the migration deficiency of CD4+ T cells primed in an IL-10-enriched environment, as is the case of ESAT-6-specific T cells, which may have a detrimental impact in the long-lasting control of infection." (PMID 35935958, 2022). "Thus, IL-10 has a significant impact on the differentiation of T cells during the early stage of infection." (PMID 36189368, 2022). "The elevated level of IL-10 in these children is noteworthy and highlights (as in the case of Shigella) the host’s effort to control inflammation and prevent intestinal epithelial damage during early stages of infection." (PMID 35924851, 2022). "It is important to remark that the control of IL-10 production is needed in stressed conditions since it is described that high IL-10 production leads to a suppression of the immune response and, therefore, a failure to control the infection." (PMID 36290599, 2022). "However, treatment with either 40 mM or 80 mM significantly increased the level of IL-10 at 4 weeks, before the levels were significantly reduced at 8 weeks post-infection in the L-GSH-treated animals, compared to the untreated controls." (PMID 35453358, 2022). "Further, it was also observed that production of IL-10 during entire time of infection remains high in mice infected with lethal (P. berghei and P. yoelii 17XL) that might correlate with increased parasitaemia and haemozoin accumulation." (PMID 35109868, 2022).
infection (continued). "RT‐qPCR experiments showed that Kp52145 infection increased the levels of the M(Kp) markers arg1, il10, nos2, the ISG isg56 and ido in THP‐1 cells in a STAT6‐dependent manner because the STAT6 inhibitor AS1517499 abrogated Klebsiella‐mediated upregulation of these M(Kp) markers." (PMID 36337046, 2022). "Of note, IL-10 exhibited progressively enhanced levels with increasing infection time." (PMID 35617354, 2022). "This is related to the fact that, to ensure their survival, these parasitic worms modulate the human immune system in the chronic phase of their infection through induction of IL-10-driven immunoregulatory responses that act, in a so-called ‘bystander’ way, to suppress allergic inflammation." (PMID 36572891, 2022). "In addition, p65 mRNA expression levels decreased in PCV2-infected 3D4/2 cells at 8, 12 or 24 h post-infection (p < 0.05 or p < 0.01), and IL-10 mRNA expression levels decreased in PCV2-infected 3D4/2 cells at 8 and 12 h post-infection (p < 0.05)." (PMID 35624806, 2022). "This further suggests IL-10 could be a sensitive biomarker for predicting infection and bleeding following TTPB." (PMID 36154663, 2022). "This suggests that IL-10-producing B cells may also play an important role in immunosuppression at an early stage of infection, before to induction of Tregs." (PMID 36618354, 2022). "Also, the Att-S74-T3Bo-infected calves developed significant levels of IL-10 at days 3 and 6 post-infection, and IL-4 at day 12 post-infection." (PMID 36466866, 2022). "As peripheral levels of IL-10 were correlated with the tissue cell-associated SIV-DNA content during chronic infection, we next sought to determine whether in situ levels of IL-10 in LNs were similarly tied to the extent of infection." (PMID 35230978, 2022). "We observed an increase in IL-10 expression at an early stage of infection in PBMCs infected with a heterologous strain, which may indicate a serious inflammatory process compared to cells infected with a homologous strain." (PMID 36032295, 2022). "Additionally, Tnf and Il10 transcripts were increased in the E8.5 infection group only, and multivariate modeling confirmed that only infection at this day significantly predicted these increases." (PMID 35312688, 2022). "However, IFN-γ/IL-10 ratio in mice treated with ZIL at 7 d post-infection was greater than 1 indicating a favorable Th1 immune response which is known to be important for the control of intracellular pathogens." (PMID 36039381, 2022). "From an immunological point of view, VL is characterized as a disease marked by the host’s inefficiency in eliminating the parasite, which is mainly determined by the presence of serum IL-10 despite the expressive Th1 profile activation present in the infection." (PMID 36668925, 2022). "The study further examined different key immune genes such as the transcript level of tumor necrosis factor-alpha (TNFα), interleukin-6 (IL-6), interleukin-8 (IL-8), interleukin-10 (IL-10), interleukin-1 beta (IL-1β), and transforming growth factor-beta 1 (TGFβ1) during the early phase of infection." (PMID 36145441, 2022). "Importantly, the infection of the IL-10-eGFP mice resulted in comparable levels of infectious centers in the bone marrow, spleens and lymph nodes as in the wild-type (wt) BALB/c mice." (PMID 36527061, 2022). "The immunosuppressive cytokine IL-10 is known as a T helper 2 (Th2) effector molecule, but it is currently unclear whether IL-10 dampens or promotes Th2 differentiation during infection." (PMID 35428872, 2022). "However, hemolymph did not influence the production ofIFN-γ, IL-12, IL-6, and IL-10 during infection." (PMID 35910486, 2022). "However, in case of infection by non-lethal (P. chabaudi and P. yoelii 17XNL), the expression of IL-10 is very low during early stage of infection giving ample opportunity for effective immune activation and leading to parasite clearance." (PMID 35109868, 2022).
infection (continued). "The increased expression of IL-10 in situ in IL-32γTg mice may be one of the relevant mechanisms involved in the control and immunopathogenesis of the experimental infection against this protozoan." (PMID 35097133, 2022). "However, the brains of IL-10-/- mice had a higher percentage of ILC3 cells producing TGFβ1 3 days after infection, and by day 5, both the number and percentage of TGFβ1-positive ILC3s were higher in IL-10-/- mice than WT mice." (PMID 36016413, 2022). "The IL-10 gene was upregulated at 6, 12, 24, and 48 hours after infection in the planktonic group; in the biofilm group, the IL-10 gene was downregulated at 6 hours after infection but upregulated at 12, 24, and 48 hours after infection." (PMID 35677656, 2022). "Particularly, IL-6 is considered a crucial cytokine for developing an antigen-specific humoral response during some infections, and IL-10 is an important anti-inflammatory cytokine that downregulates the production of pro-inflammatory cytokines and generally protects from systemic inflammation." (PMID 36497139, 2022). "The critical role of the potent anti-inflammatory cytokine IL-10 during host infection involves the modulation of both innate and adaptive immunity through the suppression of T cells, NK, and macrophages, helping to protect from the effects of excessive and prolonged inflammation." (PMID 36362383, 2022). "S. aureus has been shown to promote IL-10 production to extend its survival during infection." (PMID 35776778, 2022). "Next, we evaluated the immune response associated with the immunization by analyzing the expression of major proinflammatory (IFN-γ) and disease promoting (IL-10 and IL-4) cytokines in the splenocytes of LmexCen−/− and LmexWT injected hamsters at 11 weeks post-infection." (PMID 36463228, 2022). "Furthermore, infection of human cells with L. braziliensis increased the production of TNFα and IL-10 in a TLR4-dependent manner, reinforcing the role of TLR4 as an important receptor in Leishmania infections." (PMID 35402314, 2022). "However, if IL-27 induces IL-10 at a later time during infection, immunopathology is reduced while preserving the antiviral immune response." (PMID 35634328, 2022). "IL-10 and IL-4 mRNAs are specifically enhanced within 16 h of infection." (PMID 35396684, 2022). "We wished to determine whether these novel HCMV CD8+ T cell IL-10 responses were established during primary infection or are a product of changes to the memory CD8+ T cell pool over time as the virus persists and periodically reactivates." (PMID 36558866, 2022). "Studies have shown that in experimental models of leishmaniasis, regulatory B cells play a negative role, contributing to increased susceptibility to infection by producing polyclonal antibodies and immunosuppressive cytokines (e.g. IL-10)." (PMID 36618354, 2022). "Furthermore, lower serum levels of IL-12 and IL-10 were observed in ZIL-treated mice at 14 d post-infection." (PMID 36039381, 2022). "The results of IL-10 cytokine assays revealed that the cytokine concentrations in each infection group showed various degrees of elevation, and the concentrations of Co-PRRSV-PCV2 and PRRSV-PCV2 groups were higher than in the other infection groups at 7 and 14 dpi." (PMID 35215787, 2022). "Interestingly, the infection of chickens with C. jejuni significantly upregulated (P < 0.05) the expression of the IL-10 (2.7 fold), IL-17A (2.9 fold), IL-1β (1.9 fold), IFN-γ (1.5 fold), and CXCLI1 (1.8 fold) genes compared to NC group." (PMID 36135600, 2022). "The higher the level of IL-10 in the serum, the lower the infection (sero-positivity)." (PMID 36678367, 2022). "Interestingly, the infection of the Gbl12n cells reduced IL-10 release relative to uninfected cells." (PMID 36366531, 2022). "Interestingly, we observed that patients with a critical disease course, who survived the infection, showed significantly elevated levels of IL10 in their blood." (PMID 36293090, 2022).
infection (continued). "These hybrid MDMs produced higher levels of anti-inflammatory IL-10 but showed competence in controlling infection through increased production of pro-inflammatory IL-12, reactive oxygen species, and enhanced phagocytosis, which contrasts the previous M. tb study." (PMID 36275033, 2022). "If we observe the cytokine profiling of the infectious state, TNFα shows a constant 2–3 fold change which symbolizes its role in the parasite clearance during initial infection but the fold change of IL12 (2–5 fold change) is low as compared to the fold change of IL10 (7–8 fold change)." (PMID 35011356, 2021). "However, as the infection progresses, IL-10 levels decrease and IFN-γ concentrations increase in every clinical form caused by this Leishmania species." (PMID 34169006, 2021). "In conclusion, both the Type 1 hypersensitivity response, as suggested by IL-4 expression plus the defective Type 4 hypersensitivity response abrogated by IL-10 contribute to increased infection severity and compromise the development of an effective immune response." (PMID 34035796, 2021). "IL-10 functions to inhibit the anti-mycobacterial activity of macrophages with possible mechanism of action to limit cytokine-induced tissue damage and inflammatory response during infection by inhibiting the activity of NF-κB signaling pathway in cells." (PMID 35046920, 2021). "Interestingly, serum IL-10 level subsided to normal, upon recovery, suggesting its role during the active phase of infection." (PMID 34460819, 2021). "Previous studies showed that GC B cell responses and antibody production are absent in mice treated with an anti-IL-10R blocking antibody (clone 1B1.3a) throughout the course of P. yoelii infection, and we observed Il10 mRNA expression in Plasmodium-infection induced GC-Tfh cells." (PMID 33529242, 2021). "Besides, our study also revealed an increased level of plasma IL-10 during the acute phase of the infection and is in line with the previous findings." (PMID 34946862, 2021). "The production of IL-10 may curtail undesirable inflammatory responses to A/H3N2 infection simulated in A/H3N2-challenged PBMC." (PMID 35128529, 2021). "Metacestode infection elicited high levels of IL-10 and upregulated STAT-3 in peritoneal cells." (PMID 33461599, 2021). "Further, studies of CD8+ T cell responses are complicated in CPXV infection due to the expression of other viral inhibitors of T cell immunity, including a soluble molecule that blocks costimulation and potentially the induction of interleukin-10 (IL-10) by infection (34, –, 36)." (PMID 33692206, 2021). "Interestingly, GL pretreatment effectively decreased the upregulation of pro-inflammatory cytokines (IFN-γ, TNF-α, and IL-6) induced by ST infection in spleen and liver, and increased secretion of anti-inflammatory cytokine IL-10 in spleen." (PMID 34239908, 2021). "In addition, recombinant L. lactis administered 4 weeks after infection was observed to decrease lesion size, as well as the number of parasites, and produced a higher IL-10 production and decrease IFN-γ secretion." (PMID 34248935, 2021). "Levels of three cytokines were significantly different between the toxigenic and non-toxigenic groups; IL-8 and IL-12 levels were lower in ZC-4-infected piglets at 24 and 72 h post infection, respectively, whereas IL-10 levels were higher in ZC-4-infected piglets at 48 h post infection." (PMID 33665221, 2021). "CT positive women carrying IL10 GG had a marginally, but not statistically significant, increased risk for developing complications after a CT infection (OR: 1.9, 95%CI: 1.0–3.6, p = 0.07)." (PMID 33430411, 2021). "After aerogenically infecting pMT-10 mice with M. tuberculosis, in one group we induced IL-10 overexpression starting at day 5 after infection to determine the early-phase impact of this cytokine in the ability of mice to control M. tuberculosis bacterial burdens." (PMID 34554927, 2021).
infection (continued). "Associations with infection were replicated at two SNP (IL13 rs1800925; IL4 rs2243250), and both of these SNP and also the IL10 (−1082/−819/−592) haplotype were also found to be associated with pathology, despite the studies using different phenotypes and in one case different parasite species." (PMID 33659002, 2021). "In that study, the levels of serum IL-18 were also found to be increased in parallel with those of serum IL-10 in Lm-infected B6 mice at 72 h post-infection, whereas B6.Nlrp3−/− mice had significantly reduced serum IL-18, which indicated that NLRP3 expression is relevant for IL-18 production." (PMID 35053151, 2021). "Surprisingly, we also observed that several genes related to inflammatory process (il1b, il10, tgfb) were repressed after 35 h of infection with the low dose of Gas1, and could be explained by a modified dynamic of gene expression over time." (PMID 34295335, 2021). "IL-10 plays immunoregulatory roles during a variety of infections." (PMID 34960620, 2021). "Interestingly, these neutrophils from PL treated mice produced significantly higher levels of immunosuppressive cytokine IL-10, compared to those from mice with KPn infection alone." (PMID 34135384, 2021). "This seems to indicate that the increase in IL-6, IL-8 and IL-10 is a common result of infection." (PMID 34925324, 2021). "It has been reported that pathogens inducing IL-10 at early phases of the immune response could compromise the resolution of infection, and in some cases, lead to persistent infection or promote maintenance of persistent infection." (PMID 34394113, 2021). "Therefore, microbiota-depleted IL-10−/− mice were infected with C. jejuni strain 81-176 by gavage and orally treated with Aviguard® or placebo from day 2 to 4 post-infection." (PMID 34206478, 2021). "IL-10 is a major immunomodulatory cytokine that is able to inhibit the synthesis and release of other cytokines, thereby inhibiting cell-mediated immunity and extending the duration of viremia during the early stage of infection." (PMID 33665221, 2021). "The expression of proinflammatory cytokines in general appears to be down-regulated by myxozoans, in early-stage infections, followed by a skewed anti-inflammatory response later on, characterized by massively increased il10 levels, e.g. in S. molnari, C. shasta and T. bryosalmonae." (PMID 34603313, 2021). "However, more work is necessary to identify the cellular targets of IL-10 leading to viral reactivation at these later stages of infection." (PMID 34959486, 2021). "Additionally, there was a strong trend to increased IL-10 (anti-inflammatory) shortly after infection, and a significant increase in IL-7 (drives lymphocyte development) late in infection." (PMID 33376758, 2021). "The authors first found that NK cells were the main source of IL-10 (mRNA) at 14 days post-infection with L. donovani by analyzing the purified leucocyte population from the spleen of infected mice, whereas T CD4+ and NK cells were the main sources of IL-10 production at 28 days post-infection." (PMID 35053151, 2021). "For instance, in Il10−/− mice with a low grade of intestinal inflammation, K. pneumoniae infant isolates potentiated inflammation and elicited colitis since fecal lipocalin-2 levels increased 1-month post-infection." (PMID 34204632, 2021). "Therefore, microbiota-depleted IL-10−/− mice were infected with C. jejuni by gavage and challenged with either AC or placebo via the drinking water starting on day 2 post-infection." (PMID 34209438, 2021). "In addition, a high transcription level of IL-10 in the spleen was observed at 112 dpi after infection via the IV route and was significantly higher than that in the liver." (PMID 34977224, 2021). "Therefore, the relative transcription of MUC2 and TFF3 was measured in colonic tissue samples taken at day 6 following peroral infection of secondary abiotic IL-10−/− mice." (PMID 34183045, 2021).